CECR2 (CECR2 histone acetyl-lysine reader)
Description:
Regulatory subunit of the ATP-dependent CERF-1 and CERF-5 ISWI chromatin remodeling complexes, which form ordered nucleosome arrays on chromatin and facilitate access to DNA during DNA-templated processes such as DNA replication, transcription, and repair. The complexes do not have the ability to slide mononucleosomes to the center of a DNA template. The CERF-1 ISWI chromatin remodeling complex has a lower ATP hydrolysis rate than the CERF-5 ISWI chromatin remodeling complex. Plays a role in various processes during development: required during embryogenesis for neural tube closure and inner ear development. In adults, required for spermatogenesis, via the formation of ISWI-type chromatin complexes (By similarity). In histone-modifying complexes, CECR2 recognizes and binds acylated histones: binds histones that are acetylated and/or butyrylated. May also be involved through its interaction with LRPPRC in the integration of cytoskeletal network with vesicular trafficking, nucleocytosolic shuttling, transcription, chromosome remodeling and cytokinesis.
Synonyms: KIAA1740
Tractability: Small molecule: a structure with a bound ligand is known; a high-quality ligand is known; it has a binding pocket of medium quality. PROTAC: a small molecule that binds it is known.
Target class: Epigenetic regulator; Bromodomain; Reader
Chemical probes: GNE-886 (high quality), NVS-CECR2-1 (high quality), TP-238 (high quality), bromosporine (high quality)
Gene: Protein-coding gene on chromosome 22 (17,359,949 to 17,558,151, forward strand). Ensembl gene ENSG00000099954.
Subcellular location: Nucleus
Subcellular location (Human Protein Atlas): Nucleoplasm; Vesicles
Gene Ontology:
Molecular function: ATP-dependent chromatin remodeler activity; protein binding
Biological process: chromatin remodeling; execution phase of apoptosis; apoptotic DNA fragmentation; cytoskeleton organization; cytoskeleton-dependent cytokinesis; single fertilization; vesicle-mediated transport
Cellular component: CERF complex; nucleus; euchromatin; ISWI-type complex
Genetic constraint (gnomAD): Loss-of-function variants: 26 observed, 139.36 expected, observed/expected ratio (o/e) 0.19, 90% interval 0.14 to 0.26. The upper end of that interval is the gene's LOEUF score, 0.26, which puts it in group 1 of 6, group 1 being the genes least tolerant of losing a copy. Missense variants: 1,727 observed, 1,858.5 expected, observed/expected ratio (o/e) 0.93, 90% interval 0.89 to 0.97. Synonymous variants: 717 observed, 698.52 expected, observed/expected ratio (o/e) 1.03, 90% interval 0.96 to 1.09.
Homologues: Orthologues: chimpanzee CECR2 (99% identical), macaque CECR2 (96% identical), rat Cecr2 (83% identical), guinea pig CECR2 (82% identical), mouse Cecr2 (81% identical), dog CECR2 (78% identical), rabbit CECR2 (76% identical), pig CECR2 (73% identical), tropical clawed frog cecr2 (40% identical), zebrafish cecr2 (32% identical), Caenorhabditis elegans baz-2 (5% identical), Drosophila melanogaster Acf (5% identical). Paralogues in human: BRD4 (14% identical), BRDT (11% identical), BPTF (11% identical), BRD2 (11% identical), BRD3 (10% identical), BAZ2B (9% identical), BAZ2A (8% identical), BAZ1A (7% identical), BAZ1B (6% identical), KAT2B (5% identical), KAT2A (5% identical).
Diseases named in the same sentence as CECR2 in open-access papers:
CECR2 is named in the same sentence as 26 diseases in open-access papers, as found by Europe PMC text mining. Sharing a sentence is not in itself a finding about the gene and the disease. The quoted sentences say what the papers report.
cat-eye syndrome (8 papers, 2012 to 2023). Cat eye syndrome (CES) is a rare chromosomal disorder with a highly variable clinical presentation. "The other component of the complex, CECR2 (cat eye syndrome chromosome region candidate 2) is associated to the human disorder cat eye syndrome, and its deletion causes exencephaly in mice." (PMID 29686607, 2018). "The duplicated region completely overlapped with the 22q11.21 recurrent (Cat eye syndrome) region (includes CECR2) (chr22:17,392,953–18,591,860), and the current ClinGen database three-star dosage sensitivity score was 3, indicating clarify pathogenic variants." (PMID 37880750, 2023). "Thirdly, both case 20 (de novo) and case 21 (maternally inherited) involved 22q11.1q11.21 duplication affecting the morbid genes TBX1 (MIM: 602054) and CECR2 (MIM: 115470); furthermore, the duplication region partially overlapped with a critical region of cat eye syndrome (CES)." (PMID 35806909, 2022). "One of the recently developed non-BET BRD inhibitors is NVS-CECR2-1, which targets cat eye syndrome chromosome region, candidate 2 (CECR2)." (PMID 33004947, 2020).
breast carcinoma (7 papers, 2021 to 2025). "Upregulation of CECR2 in breast cancer metastasis is also attributed to the modulation of tumor immunity by promoting M2 macrophage polarization to create an immunosuppressive environment." (PMID 41278204, 2025). "Among genes in 22q11.21 region, CECR2 as an epigenetic factor plays a vital role in DNA damage responses, which has also been reported to promote breast cancer metastasis via NF-kB and regulate macrophage." (PMID 37393256, 2023). "In this respect, upregulation of CECR2 in metastatic breast cancer is positively related to M2 macrophages and increases tumor metastasis by promoting M2 macrophage polarization to create an immunosuppressive microenvironment." (PMID 34736517, 2021). "Correspondingly, the inhibition of CECR2 by targeting bromodomain arrests immunosuppression by macrophages and inhibits breast cancer metastasis." (PMID 34736517, 2021). "Recently, CECR2 was identified as a critical epigenetic regulator that interacts with acetylated RelA, increasing the expression of NF-κB target pro-inflammatory genes and driving breast cancer metastasis." (PMID 39713312, 2024). "In addition, cat eye syndrome chromosome region candidate 2 (CECR2) is an epigenetic regulator which is necessary for breast cancer metastasis." (PMID 37509382, 2023). "The molecular and clinical implications of CECR2 in cancer remain largely unknown, although a very recent report revealed that CECR2 is a driver for breast cancer metastasis by promoting NF-kB signaling and macrophage-mediated immune suppression." (PMID 36674511, 2023). "They found that CECR2 promotes breast cancer metastasis by regulating M2 TAMs." (PMID 37509382, 2023). "Considering the role of CECR2 in modulating the immune response in the breast cancer tumor microenvironment and promoting metastasis, utilizing this agent to achieve an immune-responsive tumor microenvironment might be a promising approach to counter metastatic breast cancer with upregulated CECR2." (PMID 41278204, 2025). "Pharmacological inhibition of the acetyl-lysine reader, cat eye syndrome chromosome region candidate 2 (CECR2), has been found to impede macrophage-mediated NF-κB immunosuppression and to inhibit breast cancer metastasis." (PMID 39135991, 2024).
coloboma (2 papers, 2021 to 2024). An abnormality in which a part of a structure in one or both eyes is missing. "Microphthalmia, seen in 19–39% of patients with CES2,3, was also seen with both presumptive null Cecr2 mutations on this background, but only associated with coloboma and at a lower penetrance than in humans (8.3–10%)." (PMID 33542446, 2021). "The coloboma phenotype that suggests a role for Cecr2 in CES only appeared when the mutations were crossed onto a C57Bl/6N background, highlighting the importance of strain differences when studying a complex phenotype." (PMID 33542446, 2021). "Cecr2 KO exhibits a variety of defects (coloboma, microphthalmia, and skeletal, heart, and kidney defects), but none of them were described in hematopoiesis." (PMID 38424235, 2024). "We have now shown that Cecr2 heterozygotes also have a low penetrance of coloboma, microphthalmia, tail kinks and polydactyly." (PMID 33542446, 2021). "In this study we have shown that deleterious loss of function mutations in mouse Cecr2 effectively demonstrate many of the abnormal features present in human patients with CES, including coloboma and specific skeletal, kidney and heart defects." (PMID 33542446, 2021). "Here we show that mice homozygous for mutations in Cecr2 show coloboma, microphthalmia, and skeletal, heart, and kidney defects at variable penetrance in a strain specific manner, recapitulating many of the features of human CES associated with the gain of CECR2 copies." (PMID 33542446, 2021). "Unlike Cecr2Del/Del, no embryos with coloboma (p < 0.0001) or microphthalmia (p > 0.05) were seen in Cecr2+/+ littermates (0/29, 0%)." (PMID 33542446, 2021). "No BALB/cCrlAlt Cecr2+/+ littermates sectioned had coloboma (0/2, 0%)." (PMID 33542446, 2021).
cephalocele (1 paper, 2016). A congenital neural tube closure defect resulting in the protrusion of the brain through a skull opening. "Mice deficient in Cecr2 primarily exhibit exencephaly but also present a midline facial cleft with exencephaly or forebrain cephalocele in a different genetic background." (PMID 26989192, 2016).
chronic myelogenous leukemia (1 paper, 2020). "To further substantiate these results, we analyzed the HAP1 cells, a near-haploid human cell line derived from the chronic myelogenous leukemia cell line KBM-7, in which the gene coding for CECR2 was knocked out by the CRISP/Cas9 system." (PMID 33004947, 2020).
colon cancer (1 paper, 2020). "In addition, CECR2 expression levels vary even among different cancer cells with same tissue origin- a panel of colon cancer cell lines, and the requirement of CECR2 for cell viability is correlated with its expression levels." (PMID 33004947, 2020).
colorectal adenocarcinoma (1 paper, 2020). The most common type of colorectal carcinoma. "However, both colorectal normal and colorectal adenocarcinoma tissues showed medium or high levels of CECR2 staining." (PMID 33004947, 2020).
colorectal cancer (1 paper, 2020). A primary or metastatic malignant neoplasm that affects the colon or rectum. "To evaluate the clinical significance of our findings, we analyzed the CECR2 gene expression in human colorectal cancer using several online databases." (PMID 33004947, 2020). "First, the data from TCGA Pan-Cancer Atlas showed that CECR2 mRNA expression in colorectal cancer ranked at a moderate to medium level among the 32 different cancer types, comprising 10,967 samples from 10,953 patients." (PMID 33004947, 2020). "A differential analysis of normal and cancer tissues in the 11 colorectal datasets comprising 2033 samples showed that CECR2 mRNA expression was upregulated in colorectal cancer tissues compared to colorectal normal tissues." (PMID 33004947, 2020). "In support of this, a differential analysis showed that CECR2 mRNA expression is upregulated in colorectal cancer tissues compared to normal counterparts." (PMID 33004947, 2020). "Immunohistochemical staining data from the Human Protein Atlas revealed that colorectal cancer belonged to a group in which 100% of examined patients displayed medium or high levels of CECR2 protein expression." (PMID 33004947, 2020). "We also performed analysis of CECR2 gene expression in colorectal cancer tissues using several online databases and discussed the significance of the results." (PMID 33004947, 2020). "Thus, it is not conclusive at the moment whether CECR2 is a therapeutic target for colorectal cancer and NVS-CECR2-1 is clinically applicable in treatment of this cancer type." (PMID 33004947, 2020). "However, immunohistochemical staining of CECR2 scored high or medium levels in both colorectal normal and adenocarcinoma tissues from several patients, and CECR2 was not defined as a prognostic gene in colorectal cancer based on the Kaplan–Meier survival curves." (PMID 33004947, 2020).
congenital heart disease (1 paper, 2023). A heart disease that is present at birth. "Among these genes, amplification of the genes CECR2, SLC25A18 and ATP6V1E1, mapping within the critical region for CES, may be responsible for iris coloboma,congenital heart disease, craniofacial anomalies in patients with CES." (PMID 37880750, 2023).
folate deficiency (1 paper, 2025). A nutritional condition produced by a deficiency of FOLIC ACID in the diet. "Studies have demonstrated that folate increased CECR2 expression, while folate deficiency and the resulting increase in homocysteine levels, especially its metabolite homocysteine thiolactone, led to a decreased expression of CECR2." (PMID 40869924, 2025).
polydactyly (1 paper, 2021). A disease characterized by the presence of polydactyly, including syndromic and non-syndromic forms. "We show that Cecr2 homozygotes can have post- and pre-axial polydactyly, of which only pre-axial involves cartilage or bone." (PMID 33542446, 2021).
cancer (7 papers, 2019 to 2025). A tumor composed of atypical neoplastic, often pleomorphic cells that invade other tissues. "Thus, targeting CECR2 and its bromodomain activity represents a promising target for modulating NF-κB signaling and associated inflammation in cancer." (PMID 39713312, 2024). "The sensitivity of the cancer cells to NVS-CECR2-1 is reduced by CECR2 depletion, suggesting that NVS-CECR2-1 exerts its activity by targeting CECR2." (PMID 33004947, 2020). "The exact role of CECR2 in the cancer cell viability and its effects on the cell sensitivity to NVS-CECR2-1 remain to be clearly defined in future study." (PMID 33004947, 2020). "Our data showed that the cytotoxic activity of NVS-CECR2-1 on cancer cells is exerted by targeting CECR2 as well as via CECR2-independent mechanism." (PMID 33004947, 2020). "The cytotoxic activity of NVS-CECR2-1 against the cancer cells is reduced by CECR2 depletion and is positively correlated with the extent to which the cells rely on CECR2 for their survival, suggesting that NVS-CECR2-1 exerts its activity by targeting CECR2." (PMID 33004947, 2020). "CECR2 was recently recognized as a ‘top epigenetic regulator’ that upregulates NF-κB inflammatory and pro-metastatic genes, emphasizing the therapeutic potential of targeting this bromodomain-containing protein in cancer treatment." (PMID 39713312, 2024). "Interestingly, treatment with a CECR2 inhibitor restrains M2 polarization induced by cancer cells and suppresses cancer cell metastatic potential." (PMID 38892411, 2024). "Interestingly, our data show that NVS-CECR2-1 also kills cancer cells by CECR2-independent mechanism." (PMID 33004947, 2020). "By contrast, in human PDA tumors, containing cancer and stromal cell types, nearly all HDACs (except SIRT4) and BETs (except BRDT, BRWD3, and CECR2) were highly expressed." (PMID 33244070, 2020). "Therefore, the cytotoxic activity of NVS-CECR2-1 on cancer cells is not necessarily dependent on CECR2 expression." (PMID 33004947, 2020).
tumor (4 papers, 2021 to 2025). "Some tumor suppressors such as down-regulation of candidate 2 (CECR2), contribute to tumor growth in laryngeal squamous cell carcinoma." (PMID 36045700, 2021). "CECR2 has been found to be involved in the regulation of tumor immunity via macrophages." (PMID 34736517, 2021). "Moreover, CECR2 was also upregulated in our tumor samples, suggesting that the gene may act as a potential oncogene in early ESCC." (PMID 37393256, 2023).
CECR2 also shares sentences with these, for which no sentence is quoted: microphthalmia (2 papers); adenocarcinoma (1); anencephaly (1); colon adenocarcinoma (1); Hydrocephalus (1); iris coloboma (1); leukemia (1); liver cancer (1); melanoma (1); meningoencephalocele (1); neurodevelopmental disorder (1); rectal adenocarcinoma (1); spina bifida (1).